ACOX1 (acyl-CoA oxidase 1)
Description:
Involved in the initial and rate-limiting step of peroxisomal beta-oxidation of straight-chain saturated and unsaturated very-long-chain fatty acids (VLCFAs). Catalyzes the desaturation of fatty acyl-CoAs that have a saturated bond between C2 and C3 (2,3-saturated acyl-CoA) to 2-trans-enoyl-CoAs ((2E)-enoyl-CoAs), and donates electrons directly to molecular oxygen (O(2)), thereby producing hydrogen peroxide (H(2)O(2)). May play a role in peroxisomal beta-oxidation step in polyunsaturated fatty acids (PUFAs) biosynthesis. Possibly regulates systemic levels of docosahexaenoic acid (DHA, C22:6n-3) through a process involving endoplasmic reticulum desaturation and elongation of alpha-linolenic acid (ALA, C18:3n-3) to form tetracosahexaenoic acid (THA, C24:6n-3), which is then beta-oxidized to DHA in peroxisomes (Probable). Involved in VLCFA-dependent hepatic-to-adipose tissue inter-organ signaling in response to diet. Through hepatic beta-oxidation of THA, may regulate THA systemic levels and THA-dependent activation of FFAR4 signaling in adipocytes, limiting adipose tissue thermogenesis (By similarity). [Isoform 1]: Shows highest activity against medium-chain fatty acyl-CoAs. Shows optimum activity with a chain length of 10 carbons (decanoyl-CoA) in vitro. [Isoform 2]: Is active against a much broader range of substrates and shows activity towards long-chain and very-long-chain fatty acyl-CoAs.
Synonyms: AOX; SCOX; ACOX; PALMCOX; MITCH
Tractability: PROTAC: ubiquitination databases record sites on it; its protein half-life has been measured; a small molecule that binds it is known.
Target class: Enzyme; Oxidoreductase
Gene: Protein-coding gene on chromosome 17 (75,941,507 to 75,979,459, reverse strand). Ensembl gene ENSG00000161533.
Subcellular location: Peroxisome
Subcellular location (Human Protein Atlas): Peroxisomes; Nucleoli
Pathways (Reactome):
Metabolism: Beta-oxidation of very long chain fatty acids; PPARA activates gene expression; alpha-linolenic acid (ALA) metabolism
Protein localization: Peroxisomal protein import; TYSND1 cleaves peroxisomal proteins
Gene Ontology:
Molecular function: acyl-CoA oxidase activity; PDZ domain binding; protein binding; protein homodimerization activity; fatty acid binding; flavin adenine dinucleotide binding; long-chain fatty acyl-CoA oxidase activity; FAD binding; medium-chain fatty acyl-CoA oxidase activity; oxidoreductase activity; oxidoreductase activity, acting on the CH-CH group of donors; very-long-chain fatty acyl-CoA oxidase activity
Biological process: fatty acid beta-oxidation using acyl-CoA oxidase; fatty acid catabolic process; fatty acid oxidation; generation of precursor metabolites and energy; hydrogen peroxide biosynthetic process; lipid metabolic process; prostaglandin metabolic process; very long-chain fatty acid beta-oxidation; very long-chain fatty acid metabolic process; fatty acid beta-oxidation; fatty acid metabolic process
Cellular component: membrane; peroxisome; cytosol; peroxisomal matrix
Genetic constraint (gnomAD): Loss-of-function variants: 40 observed, 77.73 expected, observed/expected ratio (o/e) 0.51, 90% interval 0.4 to 0.67. The upper end of that interval is the gene's LOEUF score, 0.67, which puts it in group 2 of 6, group 1 being the genes least tolerant of losing a copy. Missense variants: 627 observed, 875.49 expected, observed/expected ratio (o/e) 0.72, 90% interval 0.67 to 0.76. Synonymous variants: 303 observed, 313.17 expected, observed/expected ratio (o/e) 0.97, 90% interval 0.88 to 1.06.
Gene-disease validity (ClinGen):
ClinGen rates the evidence that ACOX1 causes each of these diseases.
Mitchell syndrome (autosomal dominant): Definitive. A peroxisomal disease characterized by progressive episodic demyelination, sensorimotor polyneuropathy, and hearing loss that has material basis in heterozygous mutation in the ACOX1 gene on chromosome 17q25.1.
peroxisomal acyl-CoA oxidase deficiency (autosomal recessive): Definitive. Peroxisomal acyl-CoA oxidase deficiency is a rare neurodegenerative disorder that belongs to the group of inherited peroxisomal disorders and is characterized by hypotonia and seizures in the neonatal period and neurological regression in early infancy.
Homologues: Orthologues: macaque ACOX1 (99% identical), chimpanzee ACOX1 (96% identical), dog ACOX1 (89% identical), rat Acox1 (86% identical), pig ACOX1 (86% identical), rabbit ACOX1 (85% identical), mouse Acox1 (85% identical), guinea pig ACOX1 (85% identical), tropical clawed frog acox1 (76% identical), zebrafish acox1 (70% identical), Caenorhabditis elegans acox-1.1 (43% identical), Caenorhabditis elegans acox-1.4 (42% identical), and 6 more. Paralogues in human: ACOX2 (45% identical), ACOX3 (25% identical), ACOXL (20% identical), ACADVL (15% identical), ACAD9 (14% identical), IVD (13% identical), ACADL (13% identical), ACADM (13% identical), ACADS (12% identical), ACAD8 (11% identical), GCDH (11% identical), ACADSB (11% identical), and 2 more.
Diseases named in the same sentence as ACOX1 in open-access papers:
ACOX1 is named in the same sentence as 117 diseases in open-access papers, as found by Europe PMC text mining. Sharing a sentence is not in itself a finding about the gene and the disease. The quoted sentences say what the papers report.
Hepatic steatosis (59 papers, 2009 to 2025). Steatosis is a term used to denote lipid accumulation within hepatocytes. "A study conducted in 2020 showed that liver-specific ACOX1 knockout protected mice against hepatic steatosis caused by starvation or HFD due to induction of autophagic degradation of lipid droplets." (PMID 40943222, 2025). "ACOX1-deficient mice exhibit spontaneous hepatic steatosis and steatohepatitis." (PMID 34093169, 2021). "Alterations in ACOX1 and ACOX2 have been implicated in hepatic steatosis and its progression to hepatocellular carcinoma, suggesting a potential association between impaired peroxisomal β-oxidation deficiency and liver pathology." (PMID 40943222, 2025). "Of those commonly upregulated, Acox1, Acot1, and Acot2 are all involved in lipid catabolism, lipid synthesis, liver inflammation, and hepatic steatosis." (PMID 38787127, 2024). "Combining ACOX1-specific inhibitors with low-dose obeticholic acid effectively treats high-fat diet-induced hepatic steatosis and reduces serum LDL." (PMID 38595921, 2024). "Previous studies have shown that ACOX1 gene liver-specific knockout reduced hepatic steatosis induced by starvation or a high-fat diet in mice and that the ACOX1-specific inhibitor 10,12-tricosadiynoic acid alleviated hepatic steatosis in rats." (PMID 38595921, 2024). "A high-fat diet can reduce the expressions of PPARα, Cpt1α, and Acox1 genes in the liver of model group mice, indicating that the lipid oxidative metabolism pathway of non-alcoholic fatty liver mice was blocked by a high-fat diet." (PMID 37299470, 2023). "The findings of our study demonstrate that SSC enhances fatty acid oxidation by activating PPARα-mediated gene transcription and increases CPT1 and ACOX1 activity, thereby counteracting hepatic steatosis." (PMID 35628280, 2022). "Based on our in vivo and in vitro results, AO markedly stimulated lipid consumption and attenuated liver steatosis accompanied by the activation of PPARα and ACOX1." (PMID 35087411, 2021). "By contrast to Ppara-/- mice, which exhibit mild hepatic steatosis, Acox1 null mice develop strong hepatic steatosis, showing a hepatic peroxisome proliferation and the sustained activation of PPARα and expression of its target genes." (PMID 34445672, 2021). "Collectively, our study provided critical evidence that the inhibition of ACOX1 aggravated HFSW-induced liver steatosis by promoting lipid de novo synthesis and inhibiting lipid consumption even in the case of autophagy activation." (PMID 35087411, 2021). "The findings of our study demonstrated that catalpol treatment enhanced fatty acid oxidation by activating PPARα-mediated gene transcription and improving CPT1 and ACOX1 activity, thereby attenuating hepatic steatosis." (PMID 32420361, 2020). "Here, we found that PEG-BR reduced SCD1 and FAS while activating PPARα and ACOX1, improving hepatic steatosis in obese mice." (PMID 33390979, 2020). "It is worth noting that a recent study has shown that p38 inhibition enhanced parenteral nutrition-induced hepatic steatosis and attenuated the expression of Cpt1a, Acox1, and Ppargc1a in a rat model." (PMID 30563203, 2018). "The results provide evidence that small molecules specifically targeting ACOX‐1 might be a potential pathway in treating alcohol‐induced fatty liver by suppressing peroxisomal oxidation of ethanol." (PMID 40496347, 2025). "10,12-Tricosadiynoic acid, an ACOX1-specific inhibitor, improves hepatic steatosis in rats." (PMID 38595921, 2024). "In addition, Acyl-coenzyme A oxidase enzyme (ACOX1) is a rate-limiting enzyme of peroxisomal beta-oxidation of long chain fatty acids exclusive of peroxisomes, alterations in ACOX1 results in hepatic steatosis." (PMID 34361064, 2021). "Moreover, the Ppara-/-, Acox1-/- double-knockout mice exhibit a few periportal clusters of steatotic hepatocytes, and (re-)expression of human ACOX1 in mice liver results in a substantial reduction in both PPARα activation and hepatic steatosis." (PMID 34445672, 2021).
Hepatic steatosis (continued). "Finally, P2rx7−/− mice developed a hepatic steatosis characterized by a reduction of Acaca, Acacb, Fasn and Acox1 mRNA expression, as well as for ACC and FAS protein expression." (PMID 29018292, 2017). "Interestingly, FGF21 overexpression partially restored the expression of PPARα and its target genes, Acox1, Hmgcs2 and Cpt1a in Creb3l3−/− mice, which might have helped to improve the hepatic steatosis." (PMID 27301791, 2016). "BPA exacerbated hepatic steatosis in the OVX HBPA group, elevating lipid/collagen deposition with reduced Mttp mRNA and upregulated β-oxidation (Acox1, Acadvl), mitochondrial uncoupling (Ucp2), ER stress (Hyou1, Atf6), and liver injury (Tgfb1, Casp8) genes." (PMID 40475995, 2025). "The toxicodynamic interaction between DIF and MDP in promoting liver steatosis is evidenced by the combined downregulation of both PPARA and ACOX1, along with increased triglyceride accumulation." (PMID 40295322, 2025). "In MAFLD, PPARα suppresses hepatic steatosis by upregulating genes involved in β-oxidation (CPT1A, carnitine palmitoyltransferase 1A; ACOX1, acyl-CoA oxidase 1) and inhibiting de novo lipogenesis (DNL)." (PMID 40564141, 2025). "Inhibition of FAO contributes to hepatic steatosis, and enzymes regulating DNL, such as FASN, and FAO, such as ACOX1, play an important role in promoting MASH." (PMID 41448428, 2025). "It has been reported that PPARα activation upregulates its target genes (LPL, ACOX1, and CPT-1a) expression, enhancing lipid degradation and fatty acid oxidation, which ameliorates hepatic steatosis, dyslipidemia, and insulin resistance." (PMID 39942052, 2025). "In this study, specific suppression of ACOX‐1 by a specific inhibitor TDYA significantly reduced liver generation of hydrogen peroxide, which suppressed ethanol metabolism and improved hepatic steatosis in fasting mice." (PMID 40496347, 2025). "In the NAFLD model of FXR−/− mice, The activation of ACOX1 is correlated with elevated serum LDL, triglycerides, and aggravated hepatic steatosis." (PMID 38595921, 2024). "As we predicted, high doses of icariin up regulated the expression of CPT1α, ACOX1, MCAD, and LCAD, key regulatory proteins of downstream fatty acid oxidation, by promoting the transcription of PPARα, which further alleviated hepatic steatosis in rats." (PMID 36677577, 2023). "In summary, we demonstrated that dapagliflozin ameliorates hepatic steatosis by decreasing the de novo lipogenesis enzyme ACC1, increasing the fatty acid oxidation enzyme ACOX1 and inducing autophagy." (PMID 34093169, 2021). "Under ER stress conditions, ATF6α knockout mice exhibited hepatic steatosis due to the inhibition of fatty acid β-oxidation, and was accompanied by reduced expression of the related genes, including PPARα, CPT1, CPT2 and ACOX1." (PMID 30081561, 2018). "A previous study demonstrated that the anti-hepatic steatosis effect of HQT in L02 hepatocytes inhibits SREBP-1 expression and increases CPT-1 and ACOX-1 expression via activation of the AMPK and PPAR-α pathways." (PMID 28293193, 2017). "In contrast, network members promoting development of hepatic steatosis, such as PPARγ, SCD, SREBF1, ACOX1, CIDEC and CFD (adipsin) are repressed during early phase and induced during the late phase of hepatic response to HF diets." (PMID 19680557, 2009). "Moreover, liver-specific knockout of the ACOX1 gene reduced serum LDL and triglyceride levels and decreased hepatic steatosis in mice." (PMID 38595921, 2024). "Improved autophagy by acyl-CoA oxidase 1 (Acox1) KO also resulted in similar protection against hepatic steatosis without affecting the expression of genes involved in lipogenesis and FA oxidation." (PMID 37524868, 2023). "Interestingly, the expression levels of hepatic steatosis-related genes, such as LXRα, C/EBPα, PPARα, ACC, ACOX1, and CPT-1, were markedly decreased in the D-Gal and melatonin cotreated group." (PMID 37886973, 2023).
Hepatic steatosis (continued). "To investigate why liver steatosis was ameliorated by GW7647 monotherapy and co-treatment, we assessed hepatic mitochondrial and peroxisomal β-oxidation-related gene expression of CPT1, 2, and ACOX1 by real-time PCR." (PMID 33177546, 2020). "Consistently, the mRNA expression levels of fatty acid oxidation-related genes, including ACOX1, CPT1, HMGCS2, and PDK4, were increased in the livers of the MHY2013-treated db/db mice, indicating that the increased AMPK/β-oxidation signaling contributes to the improvement of hepatic steatosis." (PMID 28129657, 2017). "Future in-depth studies on how lysine acetylation affects the function of ECHD, ACOX1, and FABP-1 could shed light on the etiology of drug-induced fatty liver disease and the potential therapeutic usage of uridine to modulate liver lipid metabolism and prevent drug-induced fatty liver." (PMID 24475249, 2014). "In addition, the higher circulating FFAs with KrO may result in a higher influx of fat to the liver, thereby counteracting the beneficial effects on hepatic fat oxidation (i.e., PPARA, ACOX1, PPARGC1A), altogether leading to comparable hepatic steatosis as in the HFD controls." (PMID 34444996, 2021).
Obesity (29 papers, 2011 to 2026). Accumulation of substantial excess body fat. "Dietary supplementation of ACOX1 inhibitor has the potential to be an effective strategy for treating obesity-associated metabolic disorders." (PMID 40686867, 2025). "Recent studies suggest that high levels of ACOX1 activity is associated with high fat diet and obesity, and can generate reactive oxygen species which impair mitochondrial β-oxidation." (PMID 36371454, 2022). "Acox1 has been previously studied in the context of obesity as mice deficient in Acox1 exhibit resistance to DIO through sustained Ppara activation." (PMID 34394003, 2021). "Currently, the molecular basis for (sterile) low level inflammation in Acox1-deficient mice or for that matter in the context of obesity is poorly defined." (PMID 21760938, 2011). "This work identifies hepatic peroxisomal β-oxidation as an important regulator of metabolic homeostasis and suggests that manipulation of ACOX1 or its substrates may treat obesity-associated metabolic disorders." (PMID 38760332, 2024). "Previous study confers that the knockout of ACOX1 in mice exhibits significant protection against diet-induced obesity, adipose tissue inflammation, and systemic insulin resistance." (PMID 40686867, 2025). "Liver-specific knockout of ACOX1 has been reported to promote resistance to diet-induced obesity, inflammation, and insulin resistance." (PMID 40686867, 2025). "Meanwhile, specific knockdown of hepatic Acox1 expression prevented obesity, IR, and related complications in mice with HFD." (PMID 40431433, 2025). "Liver-specific knockout of Acox1 (Acox1-LKO) protects mice from diet-induced obesity, adipose tissue inflammation, and systemic insulin resistance." (PMID 38760332, 2024). "Placental ACOX1 protein was higher in women with obesity and correlated with maternal circulating triglycerides." (PMID 36371454, 2022). "For example, miR-615-3p interacts with CPT1C in obesity and regulates ACOX1 and ALDH1B1 in uterine cancer." (PMID 33121472, 2020). "Regardless, because modulating fatty acid oxidation is an attractive therapeutic target for the treatment of obesity, further research into the mechanisms governing the divergent expression of Acox1 and Ctp1a in mice at the suckling-weaning transition are warranted." (PMID 25102070, 2014). "Following, we showed increased protein levels of β-oxidation enzymes in malignant CAAT: elevated ACOX1 protein level characterized CAAT of women with malignant tumors, independently from obesity, while elevated ACADM protein level characterized only CAAT of obese women with malignant tumors." (PMID 38247846, 2024). "The liver gene expression of the peroxisomal β-oxidation enzyme acyl-coenzyme A oxidase 1 (ACOX1), which catabolizes very long chain fatty acids (VLCFA), increases in the context of obesity, but how this pathway impacts systemic energy metabolism remains unknown." (PMID 38760332, 2024).